GLS2 (glutaminase 2)
Description:
Plays an important role in the regulation of glutamine catabolism. Promotes mitochondrial respiration and increases ATP generation in cells by catalyzing the synthesis of glutamate and alpha-ketoglutarate. Increases cellular anti-oxidant function via NADH and glutathione production. May play a role in preventing tumor proliferation.
Synonyms: GLS; GA; LGA; hLGA
Tractability: Small molecule: a structure with a bound ligand is known; a high-quality ligand is known. PROTAC: ubiquitination databases record sites on it; its protein half-life has been measured; a small molecule that binds it is known.
Target class: Enzyme; Hydrolase
Gene: Protein-coding gene on chromosome 12 (56,470,945 to 56,488,414, reverse strand). Ensembl gene ENSG00000135423.
Subcellular location: Mitochondrion
Pathways (Reactome):
Metabolism: Glutamate and glutamine metabolism
Neuronal System: Glutamate Neurotransmitter Release Cycle
Gene Ontology:
Molecular function: protein binding; glutaminase activity
Biological process: reactive oxygen species metabolic process; regulation of apoptotic process; amino acid metabolic process; L-glutamine catabolic process; glutamine metabolic process
Cellular component: mitochondrion; mitochondrial matrix
Genetic constraint (gnomAD): Loss-of-function variants: 52 observed, 80.42 expected, observed/expected ratio (o/e) 0.65, 90% interval 0.52 to 0.81. The upper end of that interval is the gene's LOEUF score, 0.81, which puts it in group 3 of 6, group 1 being the genes least tolerant of losing a copy. Missense variants: 561 observed, 776.89 expected, observed/expected ratio (o/e) 0.72, 90% interval 0.67 to 0.77. Synonymous variants: 238 observed, 282.68 expected, observed/expected ratio (o/e) 0.84, 90% interval 0.76 to 0.94.
Homologues: Orthologues: chimpanzee GLS2 (99% identical), macaque GLS2 (97% identical), pig GLS2 (96% identical), dog GLS2 (96% identical), rabbit GLS2 (95% identical), mouse Gls2 (94% identical), rat Gls2 (87% identical), guinea pig GLS2 (86% identical), tropical clawed frog gls2 (66% identical), zebrafish gls2a (65% identical), zebrafish gls2b (62% identical), Drosophila melanogaster GLS (47% identical), and 3 more. Paralogues in human: GLS (68% identical).
Diseases named in the same sentence as GLS2 in open-access papers:
GLS2 is named in the same sentence as 108 diseases in open-access papers, as found by Europe PMC text mining. Sharing a sentence is not in itself a finding about the gene and the disease. The quoted sentences say what the papers report.
breast cancer (33 papers, 2011 to 2026). A primary or metastatic malignant neoplasm involving the breast. "Increases in GLS expression and its specific activity have been implicated in several human cancers, although GLS2 has also been shown to be important in luminal-subtype breast cancer." (PMID 39662828, 2024). "High expression of GLS2 in patients with breast cancer is inversely associated with the EMT program." (PMID 38017510, 2023). "For example, in breast cancer, GLS2 amplification or overexpression is associated with acquisition of a malignant phenotype and poor prognosis." (PMID 36851539, 2023). "For TNBC, CD44, FDFT1, G6PD, and GLS2 were significantly associated with breast cancer grade (all p < 0.05)." (PMID 35154262, 2021). "In breast cancer, GLS2 was linked to enhanced in vitro cell migration and invasion and in vivo lung metastasis." (PMID 34094960, 2021). "We also found that GLS2 expression was associated with an extremely poor prognosis in colon, ovarian, and breast cancer." (PMID 30871151, 2019). "GLS2 was recently implicated in luminal subtype breast cancer." (PMID 39662828, 2024). "However, increased expression of GLS2 promoted metastasis and increased mortality risk in breast cancer." (PMID 34094960, 2021). "Furthermore, in breast cancer patients, high GLS2 expression is associated with improved survival." (PMID 31652551, 2019). "GLS2 levels are relatively high in Luminal A and Luminal B breast cancers, while GLS1 levels are higher in TNBC, with a significant negative correlation between the expressions of GLS1 and GLS2." (PMID 39973065, 2025). "GATA3’s involvement in amino acid metabolism regulation is supported by studies in breast cancer, where Glutaminase 2 (GLS2), transcriptionally regulated by the estrogen receptor co-factor GATA3, is more common in hormone receptor-positive tumors." (PMID 39822378, 2024). "A similar expression pattern was observed in breast cancer cell lines, with luminal-subtype cells showing high GLS2 content and basal-subtype cells showing low." (PMID 38067269, 2023). "The level of the GLS2 transcript was lower in mesenchymal breast cancer cell lines than in epithelial cells." (PMID 38067269, 2023). "The N-terminal region of GAB contains a mitochondrial targeting sequence and, indeed, GLS2 protein was detected in the mitochondrial fractions of human breast cancer cells, both wild-type an ectopically expressing GLS2." (PMID 38067269, 2023). "This discrepancy, probably resulting from differences in the criteria used, hints at the complexity of the role of GLS2 in breast cancer, which is largely due to the heterogeneity of these tumors." (PMID 38067269, 2023). "GLS2 is essential in luminal tumors, suggesting a critical role for glutamine metabolism in luminal breast cancer." (PMID 34685621, 2021). "In breast cancer, GLS2 expression is preferentially upregulated in luminal-subtype cancers via promoter methylation and GATA3, a master regulator of luminal differentiation." (PMID 33194749, 2020). "Nonetheless, EMT suppresses the GLS2 gene in breast cancer, promoting glutamine independence, less mitochondrial activity, high metastasis, and low survival to patients." (PMID 32850411, 2020). "In contrast with GLS1 which is ubiquitously expressed, GLS2 is mainly expressed in brain, liver and pancreas and is inversely associated with EMT in breast cancer and hepatocellular carcinoma cells." (PMID 32318352, 2020). "Further, we found that GLS2 copy number deletions were over-represented in the basal breast cancer subtype; a subtype with poor clinical outcomes and high metastatic potential." (PMID 31652551, 2019). "We evaluated GLS2 expression in breast cancer patients and found that, in line with our data, high GLS2 expression is inversely correlated with the EMT gene signature." (PMID 31652551, 2019).
breast cancer (continued). "In support of the idea that tumor cells with high GLS2 expression have less aggressive characteristics, we found that high GLS2 expression correlates with improved overall survival in breast cancer patients." (PMID 31652551, 2019). "However, it has been demonstrated that knocking down GLS2 in breast cancer cells can reduce cell growth and glutamine metabolism-related phenotypes." (PMID 39973065, 2025). "In fact, while the paper by Dias and colleagues clearly indicates that GLS2 overexpression elevates mesenchymal markers in several breast cancer cell lines, a study by Ramirez-Peña and colleagues demonstrated that GLS2 expression is inversely correlated with EMT in breast cancer." (PMID 38067269, 2023). "Interestingly, in luminal-subtype breast cancer cells, GLS2 expression is upregulated via GATA-binding factor 3 (GATA3), indicating that its expression pattern differs not only between tissues but, also, between cancer subtypes affecting the same tissue." (PMID 38067269, 2023). "The other neoplasm in which GLS2 plays a pro-oncogenic role is in luminal-subtype breast cancer." (PMID 38067269, 2023). "Treatment with this compound suppressed TCA cycle anaplerosis and proliferation in BPTES-resistant breast cancer cells; moreover, it reduced the tumorigenic potential of MDA-MB-453 cells, supporting a view of GLS2 as a druggable target in luminal-subtype breast cancers." (PMID 38067269, 2023). "Furthermore, GLS2 that is upregulated by GATA3 in luminal-subtype breast cancer modulated the resistance to GLS inhibitors such as BPTES." (PMID 37249801, 2023). "Interestingly, in basal-subtype breast cancer cells, GLS2 expression proved to be repressed by promoter methylation." (PMID 38067269, 2023). "Furthermore, GLS2 has been reported to be a critical glutaminase isozyme in luminal‐subtype breast cancer." (PMID 35538890, 2022). "The expression of GLS2 in luminal breast cancer cells is through GATA3." (PMID 34685621, 2021). "GLS2 and PEBP1 were significantly associated with breast cancer grade (all p < 0.05)." (PMID 35154262, 2021). "Finally, GLS2 was recently shown to be an oncogene in breast cancer in our laboratory and by other groups." (PMID 33746066, 2021). "To understand how GLS2 expression impacts breast cancer patient outcomes, we analyzed the TCGA data to determine whether GLS2 expression correlates with survival of breast cancer patients." (PMID 31652551, 2019). "Notably, when we compared amplifications and deletions of GLS2 among the PAM50 subtypes, we observed that the majority of the GLS2 copy number deletions occurred in the mesenchymal stem cell-rich basal-like breast cancer subtype." (PMID 31652551, 2019). "In our models, GLS2 expression and EMT features are inversely correlated; therefore, we tested whether GLS2 status was predictive of outcome in breast cancer patients." (PMID 31652551, 2019). "We next examined whether the expression patterns of GLUL, GLS and GLS2 found in luminal and basal cell lines were also reflected in the respective subtypes of primary human breast cancers." (PMID 21852960, 2011). "In contrast, expression of GLS2 can also be promoted by the oncogenic n-Myc protein, and upregulated GLS2 expression in breast cancer tissues is found to be correlated with poor patient prognosis, indicating that the function of GLS2 may not be strictly suppressive." (PMID 39211039, 2024). "Additionally, an ectopic expression of GLS2 in SUM159 mesenchymal breast cancer cells enhanced mitochondrial activity and Gln consumption; it also inhibited mammosphere formation, which is a component of cancer-stem-cell potential, although it did not affect the proliferation of these cells." (PMID 38067269, 2023). "However, GLS2 has been reported as an oncogene in breast cancer and cervical cancer." (PMID 34094960, 2021).
breast cancer (continued). "Firstly, as the most frequently used glutaminase inhibitors such as BPTES and CB-839 are GLS1 selective, the resistance to glutaminase inhibition may be due to the differential expression of GLS1 and GLS2 in cells, as demonstrated in luminal and basal-like breast cancer cells." (PMID 33194749, 2020). "In vitro studies using luminal breast cancer cells were performed to investigate the effects of siRNA knockdown of glutaminase genes (GLS and GLS2) and inhibition using CB-839 on functional assays." (PMID 41898641, 2026). "The level of GLS2 protein in breast cancer cell lines correlated with that of the GATA3 transcription factor; a positive correlation between the GLS2 and GATA3 transcript levels was found in human breast cancer tissues." (PMID 38067269, 2023). "Splicing of GLS2 leads to a long transcript named GAB, initially identified in human breast cancer cells, and to a shorter transcript, LGA, originally identified in rat liver." (PMID 35008407, 2022). "TNBCs and luminal breast cancers express GLS and GLS2, respectively, and both TNBCs and luminal-subtype cancer cells use glutamine to supply the TCA cycle." (PMID 34685621, 2021). "On the other hand, the GLS2 gene codes for the liver (L-type) isozymes, named LGA, as well as for a longer isoform named GAB originally described in breast cancer cells." (PMID 33610185, 2021). "GLS2 is repressed in glioblastoma, HCC and colon cancers, while overexpressed in luminal subtype of breast cancer." (PMID 33194749, 2020). "To understand how GLS2 suppression metabolically supports the EMT, we overexpressed GLS2 in the SUM159 breast cancer cell line, a line that has mesenchymal characteristics; experiments were also performed with the same cells expressing control vector." (PMID 31652551, 2019). "To test this, we over-expressed GLS2 in the GLS2-negative and EMT-enriched breast cancer cell line SUM159." (PMID 31652551, 2019). "In line with results obtained from analysis of cell lines, expression of GLS2 is inversely correlated with GLS in 52% of the cancer types analyzed, including breast cancer." (PMID 31652551, 2019). "To determine if the GLS2 and GLS inverse expression pattern we observed in the cell lines is also evident in breast cancer patient samples, we compared GLS and GLS2 copy numbers in samples from 1075 patients using data from The Cancer Genome Atlas (TCGA)." (PMID 31652551, 2019). "In breast cancer, GLS and GLS2 are overexpressed at distinct levels depending on the histological subtype, and cells may display dependency on glutamine to survive, GLS2 being investigated as a protumorigenic gene." (PMID 37685021, 2023). "Restoration of GLS2 expression in GLS2-negative breast cancer cells rescued mitochondrial activity, enhanced glutamine utilization, and inhibited stem-cell properties." (PMID 31652551, 2019). "In a near-simultaneously published study, Dias and colleagues detected considerable amounts of GLS2 protein in 14 triple-negative (TN) breast cancer cell lines, which included basal, luminal, and mesenchymal subtypes, while a significantly lower content of GLS2 was found in four non-TN cell lines." (PMID 38067269, 2023). "The loss of GLS2 expression during EMT leads to an enhanced glutamine-independent phenotype and decreased mitochondrial activity, while GLS2 restoration in GLS2-negative breast cancer cells exhibits enhanced consumption of mitochondrial glutamine and impairs BCSC-like properties." (PMID 35736645, 2022). "We evaluated GLS2 and GLS expression levels in additional cell lines and found that GLS2 expression was reduced in mesenchymal breast cancer cell lines (e.g., SUM159, MDA231, and MDA 468) relative to the epithelial breast cancer cell line (MCF7) and that GLS expression was enhanced." (PMID 31652551, 2019).
hepatocellular carcinoma (27 papers, 2013 to 2025). A malignant tumor that arises from hepatocytes. "High GLS2 expression is associated with a significantly longer survival time in hepatocellular carcinoma." (PMID 34439127, 2021). "Importantly, a recent study implicated GLS2 in miRNA regulation through Dicer stabilization, upregulation of miR-34a and repression of Snail and metastasis in hepatocellular carcinoma (HCC) cells." (PMID 32042057, 2020). "It should be noted that, in this study, GLS2 silencing decreased the proliferation of HepG2 cells, which contrasts with several other papers documenting the tumor-suppressive role of GLS2 in hepatoma." (PMID 38067269, 2023). "According to previous studies, GLS2 expression was decreased in human hepatocellular carcinoma (HCC) due to hypermethylation." (PMID 36467089, 2022). "GLS2 expression was scarce in hepatocellular carcinomas and glioblastomas, which showed high levels of GLS." (PMID 34573287, 2021). "GLS2 repressed cell migration, invasion and metastasis of in hepatocellular carcinoma and induced growth inhibition in glioma cell lines." (PMID 34094960, 2021). "Co-expression of GLS and GLS2 transcripts has been reported in established cancer cell lines of colon, hepatoma, leukemia and breast, although protein data suggest that GLS isoforms would account for the majority of GA activity in these human tumor cells." (PMID 32042057, 2020). "It has been proposed as a tumor suppressor in hepatocellular carcinoma (HCC), where the loss of GLS2 is associated with tumor growth." (PMID 32326003, 2020). "A similar reversal of the phenotype was attained by the overexpression of GLS2 in hepatocellular carcinoma (HCC) cells." (PMID 30669455, 2019). "It has also been shown that GLS1 and GLS2 activities were increased approximately 20-fold and 6-fold, respectively, in transplanted hepatomas." (PMID 25844758, 2015). "In support of this notion, GLS1 expression is markedly elevated whereas GLS2 expression is decreased in hepatocellular carcinoma relative to normal liver tissues, and ectopic GLS2 expression reduced colony formation in vitro." (PMID 26528759, 2015). "Similar phenotype reversion was attained by overexpression of the GLS2 gene in nonsmall-cell lung carcinoma cells, while exogenous GLS2 expression reduces cell colony formation in human hepatocellular carcinoma and lung cancer cell lines." (PMID 24096582, 2014). "In this study, we found that GLS2 expression is significantly decreased in majority of human hepatocellular carcinoma (HCC)." (PMID 24797434, 2014). "Here, we determined Gls2 methylation status in 20 pairs of primary hepatocellular carcinomas, suggesting that Gls2 downregulation is attributed to its promoter hypermethylation." (PMID 24330717, 2013). "Previous study has found that elevated GLS2 could increase ROS production by facilitating the conversion of glutamate to α-KG, thereby promoting ferroptosis in hepatocellular carcinomas." (PMID 39537619, 2024). "Similarly, mitochondrial localization of the exogenous GLS2 protein was found in human lung cancer, hepatoma, and neuroblastoma cells transfected with GLS2-expressing vector." (PMID 38067269, 2023). "Moreover, the switching to GLS upregulation in combination with GLS2 repression in hepatoma cells has been found to be accompanied by malignant transformation in an experimental setting." (PMID 28939850, 2017).